YY2 (YY2 transcription factor)
Diseases named in the same sentence as YY2 in open-access papers (continued):
Sharing a sentence is not in itself a finding about the gene and the disease.
tumor (continued). "Together, these results indicated that the regulatory action of YY2 on SLC7A11 was essential for inducing tumor ferroptosis, most likely via suppression of cellular cysteine and GSH levels." (PMID 35246964, 2022). "Immunohistochemistry staining revealed that while YY2 overexpression induced lipid peroxidation in xenograft tumor lesions, SLC7A11 overexpression suppressed it." (PMID 35246964, 2022). "Here, it is determined that YY2 induces tumor cell ferroptosis and subsequently suppresses tumorigenesis by inhibiting solute carrier family 7 member 11 (SLC7A11) transcription, leading to the decreased glutathione biosynthesis." (PMID 35246964, 2022). "In this study, using transcriptomic analysis in addition to in vitro and in vivo experiments, we investigate a hitherto unrecognized function of YY2 in tumor cells ferroptosis and tumorigenesis through regulation of SLC7A11‐mediated GSH synthesis." (PMID 35246964, 2022). "In conclusion, we identified YY2 as a novel regulator of ferroptosis in tumor cells, which acted through the SLC7A11/GSH synthesis axis." (PMID 35246964, 2022). "In summary, we describe a novel mechanism of ferroptosis in tumor cells based on the negative regulation exerted by YY2 on SLC7A11 transcription, and revealed a competitive, antagonistic regulation of YY1 and YY2 on the SLC7A11 promoter." (PMID 35246964, 2022). "Therefore, SETD7-mediated methylation of YY2 at K247 positively regulates YY2-target gene’s transcription, which mediates the inhibitory function of YY2 in cell proliferation and tumour growth, and points to mutations affecting K247 methylation that could be pathologically relevant." (PMID 35326563, 2022). "It is currently understood that YY2 plays an important role in the regulation of mouse embryonic development and tumour metastasis; however, its regulation of ovarian function has not been investigated." (PMID 34180104, 2021). "Cumulatively, these results emphasize the importance of YY2 post‐translational modification to the tumour‐suppressive role of YY2 by weakening its regulation on the oncogenes it suppresses, and on the tumour suppressor genes it activates." (PMID 32969187, 2020). "Nevertheless, the fact that YY2 is down‐regulated in tumour cells indicates the possibility of using YY2 as a marker of tumour progression and prognosis." (PMID 32969187, 2020). "These facts point to the possibility of YY2 involvement in activating immunosurveillance and performing its tumour‐suppressive effect by maintaining the level of IFN‐β." (PMID 32969187, 2020). "Recent researches revealed that YY2 is also critical in suppressing tumour metastasis through its regulation on AES, a colorectal cancer (CRC) metastatic suppressor." (PMID 32969187, 2020). "For instance, YY2 expression level shows a dynamic fluctuation during brain development and significantly decreases during tumour progression." (PMID 32969187, 2020). "A previous study showed that the expression of YY2 and AES in liver metastases is significantly lower than in CRC primary tumour, as YY2 enhances AES transcriptional activity by directly binds to its promoter." (PMID 32969187, 2020). "Here we found for the first time that in contrast to YY1, which had been reported to be oncogenic, the expression level of YY2 in tumor cells and/or tissues was downregulated compared with its expression level in the normal ones." (PMID 28903375, 2017). "Immunohistochemical staining results further confirmed these tendencies: compared with normal adjacent tissues, the number of YY1 positive cells was significantly higher in tumor tissues, while the number of YY2 positive cells robustly decreased." (PMID 28903375, 2017). "Contrary to YY1, which showed a significant increase in tumor tissues, the mRNA expression level of YY2 was robustly decreased." (PMID 28903375, 2017). "Nevertheless, our results provide a new insight regarding the expression patterns of Mbtps2 and YY2, especially in tumor." (PMID 28903375, 2017).
tumor (continued). "Taken together, our data suggested that K247 in YY2 is involved in YY2-regulated cell proliferation and tumor growth." (PMID 29098080, 2017). "Immunohistochemistry staining results further confirmed that both YY2 and p21 expressions were lower in tumor tissues compared to their expressions in normal adjacent tissues." (PMID 28903375, 2017). "In this study, we showed that YY2 demonstrated an expression pattern opposite to YY1 in tumor and normal tissues." (PMID 28903375, 2017). "Next, we investigated the role of YY2 in determining tumor cell fate." (PMID 39903759, 2025). "Syngeneic graft experiments with MC38 cells overexpressing YY2 showed that BUB1B knockdown abolished the YY2 tumor suppressive effect, as well as its positive impact on chromosome missegregation, caspase‐1/GSDMD activation, IL‐1β, and cell death rate in syngeneic graft lesions." (PMID 39903759, 2025). "Together, these findings demonstrated that YY2 could boost the host immune response by enhancing CTL tumor‐killing activities." (PMID 39903759, 2025). "Whether YY2 acts as a tumor promoter or suppressor in ESCA remains to be explored as currently, no studies have examined its involvement in ESCA." (PMID 41235100, 2025). "Therefore, YY2‐induced chromosome missegregation triggers the cytosolic dsDNA response and, consequently, suppresses the tumorigenic potential by inducing tumor cell pyroptosis." (PMID 39903759, 2025). "Next, we explored whether BUB1B‐mediated chromosome missegregation was involved in YY2‐induced cytosolic dsDNA response, pyroptosis, and tumor immune response." (PMID 39903759, 2025). "Furthermore, it is revealed that YY2/BUB3‐mediated excessive CIN causes higher cell death rates and drug sensitivity, whereas residual tumor cells that survived DNA damage‐based therapy have moderate CIN and increased drug resistance." (PMID 38682484, 2024). "Furthermore, IHC staining using γH2AX showed that DNA damage in tumor lesions, which was increased by YY2 overexpression or oxaliplatin treatment alone, was further enhanced by combined oxaliplatin treatment and YY2 overexpression." (PMID 38682484, 2024). "Together, these results suggest that defects in the YY2/BUB3 pathway could contribute to CIN induction in tumor cells, most plausibly due to impaired SAC activity." (PMID 38682484, 2024). "Furthermore, the CSC marker CD44 was also upregulated in tumor lesions, while Numb showed a positive correlation with YY2." (PMID 37300334, 2023). "However, unlike YY1, which is upregulated in tumor tissues and is oncogenic, YY2 is downregulated in tumor tissues and is a tumor suppressor protein." (PMID 37444616, 2023). "Given the enhanced sensitivity toward chemotherapeutic agents of the resulting tumor cells, YY2 could be targeted in antitumor treatments." (PMID 37300334, 2023). "Morphological analysis revealed that YY2 overexpression clearly suppressed tumor growth." (PMID 37300334, 2023). "To reveal potential transcription factors involved in CSC maintenance, we extracted the top 20 transcription factors differentially expressed in stem‐like tumor spheres and identified two transcriptional factors, YY2 and GTF2H4, as having the most altered expression." (PMID 37300334, 2023). "Overall, our results clearly show that YY2 could suppress the tumor‐initiating capacity of HCC cells by inhibiting DRP1‐mediated CSC mitochondrial fission, thereby downregulating CSC asymmetric division and subsequently, exhausting the CSC pool." (PMID 37300334, 2023). "Next, we examined the role of YY2 in regulating tumor sphere formation and tumor initiation." (PMID 37300334, 2023). "Taken together, our in vitro and in vivo results indicated that YY2 could induce ferroptosis, and that ferroptosis was critical for the tumor suppressive effect of YY2." (PMID 35246964, 2022). "Furthermore, overexpressing YY2 reduced the potential for colony formation by tumor cells, whereas knocking out YY2 enhanced it." (PMID 35246964, 2022).
tumor (continued). "Hence, our results demonstrated that downregulation of SLC7A11 was essential for YY2 to induce ferroptosis and, consequently, for exerting a tumor‐suppressive effect." (PMID 35246964, 2022). "Moreover, YY2 increases tumor cell sensitivity to ferroptosis inducers, suggesting the potential of using YY2 as a novel anti‐tumor therapeutic strategy." (PMID 35246964, 2022). "To examine whether YY2 regulation of SLC7A11 was crucial for YY2‐induced tumor ferroptosis, we constructed a vector overexpressing SLC7A11 and two shRNA expression vectors targeting different sites on SLC7A11." (PMID 35246964, 2022). "SLC7A11 overexpression abrogated the tumor‐suppressive effect of YY2 overexpression." (PMID 35246964, 2022). "Our findings not only provide novel insights on the regulatory mechanism of ferroptosis, but also elucidate the molecular pathway underlying the tumor suppressive effect of YY2, as well as the antagonistic regulation of tumorigenic potential by the balance between YY1 and YY2." (PMID 35246964, 2022). "Next, to determine whether SLC7A11 was essential for the YY2 tumor suppressive effect, we performed xenograft experiments using a stable HCT116 cell line overexpressing both YY2 and SLC7A11." (PMID 35246964, 2022). "Moreover, mutations of YY2 zinc‐finger domains in clinical cancer patients abrogate YY2/SLC7A11 axis and tumor cell ferroptosis." (PMID 35246964, 2022). "Finally, these findings demonstrate that homeostasis between YY1 and YY2 is crucial for maintaining redox homeostasis in tumor cells." (PMID 35246964, 2022). "Together, these results clearly demonstrated that YY2 is a tumor suppressor." (PMID 35246964, 2022). "This subsequently attenuates YY2 inhibitory effect on cell proliferation and tumour growth." (PMID 32969187, 2020). "Together, these suggest that YY2 might also be involved in regulating glucose metabolism in tumour cells." (PMID 32969187, 2020). "Furthermore, we and other groups have demonstrated that YY2 is crucial in regulating tumour generation and progression, as it is critical in regulating tumour cell proliferation, cell cycle arrest, metastasis, and metabolic reprogramming." (PMID 32969187, 2020). "Overall, while the understandings regarding its molecular mechanisms have not been totally elucidated yet, the findings regarding its role in regulating tumour cells proliferation, metastasis and metabolic reprogramming point out the importance of YY2 as a tumour‐suppressive gene." (PMID 32969187, 2020). "While the specific roles of YY2 need to be examined more extensively, some studies have hinted that YY2 might affect tumour metabolism." (PMID 32969187, 2020). "In addition to the aberrant regulation of YY2 expression in tumours, YY2 has also been shown to exert its tumour‐suppressive role through its regulation by post‐translational modification." (PMID 32969187, 2020). "These facts clearly point to the possibility that YY2 could suppress not only tumour cell proliferation, but also tumour metastasis." (PMID 32969187, 2020). "Consequently, YY2 down‐regulation promotes cell cycle progression and enhances tumour cells proliferation." (PMID 32969187, 2020). "However, despite that present understanding suggests its possible involvement, the detail roles and regulatory mechanism of YY2 in immune system, especially in tumour immunity, need further investigations." (PMID 32969187, 2020). "YY2 expression is also closely related to diseases, as it could act as a tumour suppressor gene that regulates tumour cell proliferation and metastasis." (PMID 32969187, 2020). "Thus, these evidences suggest the possibility that YY2 negatively regulates tumour cells lipid accumulation." (PMID 32969187, 2020). "Herein, we summarize the current perspectives of the roles of YY2 in tumour biology." (PMID 32969187, 2020).
tumor (continued). "Consequently, YY2 inhibitory effect on cell proliferation and tumor growth was dependent on YY2 K247, revealing an intimate link between YY2 methylation and its physiological functions." (PMID 29098080, 2017). "Together, these data consistently showed that YY2 expression was lower in tumor cells and tissues, and thus might be involved in tumorigenesis in the manner totally different from that of YY1." (PMID 28903375, 2017). "Furthermore, YY2’s inhibitory effects on cell proliferation and tumor growth were shown to be dependent on K247." (PMID 29098080, 2017). "Importantly, YY2-regulated gene transcription, cell proliferation and tumor growth were dependent, at least partially, on YY2 K247 methylation." (PMID 29098080, 2017). "Together, these results indicated that in tumor cells, YY2 might act as a p21 positive regulator, and thus negatively regulate cell cycle progression and cell proliferation." (PMID 28903375, 2017). "The functional importance of YY2 K247 methylation was further supported by our observation that K247 was involved in its regulated gene transcription and inhibitory effects on cell proliferation and tumor growth." (PMID 29098080, 2017). "However, how YY2 is regulated during cell cycle and in tumor cells, as well as whether its epigenetic and/or post‐translational regulation are involved, needs further investigations." (PMID 39903759, 2025). "Some studies suggest that YY2 may function as a potential tumor suppressor gene." (PMID 41235100, 2025). "Hence, we examined whether YY2 augmented the ratio of cells with dysfunctional mitochondria and suppressed tumor stemness by regulating mitochondrial fission." (PMID 37300334, 2023). "Similarly, SLC7A11 abrogated the suppressive effect of YY2 overexpression on tumor growth rate." (PMID 35246964, 2022). "Moreover, as IL‐4 contributes to tumour growth, metastasis and chemotherapy resistance, this fact indicates that IL‐4 might be crucial for YY2‐mediated tumour suppression." (PMID 32969187, 2020). "Furthermore, we revealed that this regulatory function of YY2 could be found in various tumor cell lines, indicating that it is common in tumorigenesis." (PMID 28903375, 2017). "Moreover, whether or not these regulatory mechanisms are responsible for the aberrant YY2 expression in tumor cells remains to be elucidated." (PMID 28903375, 2017). "Mechanistically, TRIM15 degrades YY2 through the proteasome pathway, suppressing FOXRED1 transcription and ultimately accelerating tumor proliferation." (PMID 41237333, 2026). "Hyperactivation of the YY2/BUB3 axis delays mitosis, increases chromosomal instability beyond tolerable thresholds, and induces tumor cell death, thereby enhancing drug sensitivity." (PMID 41440189, 2025). "Moreover, we explored whether BUB1B was involved in YY2‐induced anti‐tumor immune response." (PMID 39903759, 2025). "Meanwhile, YY2 overexpression hyperactivates SAC, leading to prolonged mitotic time, decreased proliferation potential, and increased tumor cell death, thus suppressing tumorigenesis." (PMID 38682484, 2024). "Intriguingly, YY2 overexpression, which hyperactivates the SAC and triggers tumor suppressive effects, also induces CIN." (PMID 38682484, 2024). "This study identifies the novel role of YY2 in modulating BUB3‐mediated SAC activity and CIN, as well as YY2/BUB3‐mediated SAC activity and CIN levels role in determining tumor cell fates." (PMID 38682484, 2024). "This possibility was confirmed by a low oxygen consumption rate (OCR) in stem‐like tumor spheres with elevated YY2 levels, and a high OCR in stem‐like tumor spheres formed by HCC‐LM3YY2KO cells." (PMID 37300334, 2023).
tumor (continued). "In contrast, treatment with mDivi‐1, a dynamin inhibitor that blocks mitochondrial fission, suppressed the increase in ΔΨm observed in stem‐like tumor spheres formed by MHCC‐97HYY2KO cells, suggesting that YY2 prevented mitochondrial fission." (PMID 37300334, 2023). "To this end, we analyzed the levels of mitochondrial fission‐related genes in stem‐like tumor spheres formed by HCC‐LM3 and MHCC‐97H cells with altered YY2 expression." (PMID 37300334, 2023). "Systematic investigations elucidated that YY2 suppressed liver CSC asymmetric division, subsequently decreasing tumor‐initiating capability." (PMID 37300334, 2023). "Increasing evidences have demonstrated the tumor suppressive effect of YY2, in contrast with the oncogenic YY1; however, little is known about the biological and pathological functions of YY2." (PMID 35246964, 2022). "YY2 mRNA was relatively low in tumor lesions compared to corresponding adjacent tissues; whereas YY1 and SLC7A11 mRNA was upregulated in tumor lesions." (PMID 35246964, 2022). "Furthermore, we tested whether YY2 K247 is involved in YY2-mediated tumor growth." (PMID 29098080, 2017). "Consistently, western blotting results demonstrated that the protein expression level of YY2 showed a pattern completely different from that of YY1, as it was lower in tumor tissues than in normal adjacent tissues." (PMID 28903375, 2017). "Notably, our lipid metabolomics results showed that alterations in YY2 and FOXRED1 significantly affect the abundance of various lipid metabolites in EAC cells, regulating tumor progression mainly through the glycerophospholipid metabolic pathway." (PMID 41237333, 2026). "Animal studies showed that simultaneous knockdown of TRIM15 and YY2 counteracted the inhibitory effect of TRIM15 knockdown alone on the proliferative capacity of EAC cells, and the results of tumor oil red O staining indicated that the inhibition of lipid droplet levels was also counteracted." (PMID 41237333, 2026). "However, combination of YY2 overexpression and anti‐PDL‐L1 therapy reduced both MSI and MSS CRC tumor growth to less than four and sixfold, respectively." (PMID 39903759, 2025). "YY2 overexpression robustly increased the levels of cytosolic DNA, AIM2, ASC, cleaved caspase‐1, and GSDMD‐N, both in cells and in syngeneic graft tumor lesions." (PMID 39903759, 2025). "Moreover, the YY2/BUB1B axis is crucial for promoting CTL proliferation and activation within tumor lesions, thereby enhancing the anti‐tumor immune response." (PMID 39903759, 2025). "Taken together, our results demonstrated that YY2 promotes the formation of micronuclei and the release of dsDNA by enhancing BUB1B expression and chromosome missegregation, thereby inducing pyroptosis and the development of a tumor immune microenvironment." (PMID 39903759, 2025). "Moreover, recent studies have demonstrated competitive binding between YY2 and YY1 to identical DNA binding sites, leading to antagonistic regulation of ferroptosis in tumor cells." (PMID 41235100, 2025). "While both conditions induce CIN, a defect in YY2/SAC activity enhances mitosis and tumor growth." (PMID 38682484, 2024). "Hence, our findings provide a new perspective regarding a novel function of YY2 in regulating SAC activity and subsequently, tumor cell mitotic regulation." (PMID 38682484, 2024). "Collectively, these results demonstrated that YY2 overexpression sensitizes tumor cells to DNA damage‐inducing agent by increasing CIN, suggesting that this combination might be a potential anti‐tumor therapeutic strategy." (PMID 38682484, 2024). "Together, these results demonstrate for the first time that YY2 is a novel regulator of CSC stemness which could suppress the frequency of CSCs, thereby attenuating their tumor‐initiating capacity." (PMID 37300334, 2023).